RHOA (ras homolog family member A)
Diseases named in the same sentence as RHOA in open-access papers (continued):
Sharing a sentence is not in itself a finding about the gene and the disease.
esophageal squamous cell carcinoma (7 papers, 2011 to 2023). Esophageal squamous cell carcinoma (ESCC) is a type of esophageal carcinoma (EC) that can affect any part of the esophagus, but is usually located in the upper or middle third. "Conversely, metastasis of esophageal squamous cell carcinoma is suppressed once RhoA is inactivated due to inhibition of phosphorylation of focal adhesion kinase (FAK)." (PMID 33158289, 2020). "ROR1 strongly associates with ROR2, making up the receptor for Wnt5a signaling and activates RhoA through Daam1 in esophageal squamous cell carcinoma (ESCC) and glioblastoma." (PMID 35625853, 2022). "In esophageal squamous cell carcinoma, MME inhibits the focal adhesion kinase (FAK)- Ras homolog family member A (RhoA) signaling axis to interrupt tumor cell adhesion and metastasis, with a high MME expression level representing a favorable prognosis." (PMID 37585411, 2023).
gastric adenocarcinoma (7 papers, 2015 to 2025). "From TCGA analysis, several frequently occurring alterations have been described in GS, gastric adenocarcinoma, including mutations in CDH1 and RHOA, as well as CLDN18:ARHGAP fusions." (PMID 38717153, 2024). "RhoA mutations were identified by several groups in 2014,103 with an IntOGen search indicating a driver role for RhoA in stomach adenocarcinoma, as well as a general pan-cancer driver role." (PMID 27104658, 2016). "We observed a significant reduction in CDH1 mutations in CCNE1-amplified gastric adenocarcinoma versus nonamplified gastric adenocarcinoma (2.9% vs. 16.4%, P = 0.0002) as well as a reduction in CLDN18:ARHGAP fusions (0% vs. 6.8%); however, the frequency of RHOA mutations were similar." (PMID 38717153, 2024).
head and neck squamous cell carcinoma (7 papers, 2010 to 2022). A squamous cell carcinoma that arises from any of the following anatomic sites: lip and oral cavity, nasal cavity, paranasal sinuses, pharynx, larynx, and salivary glands. "Indeed, over expression of RHOA has been associated with colon, breast, lung, and testicular germ cell cancers as well as in head and neck squamous-cell carcinomas." (PMID 20236512, 2010). "Targeted disruption of PRKCE has been shown to reduce cell invasion and motility through inactivation of RhoA and RhoC GTPases in head and neck squamous cell carcinoma." (PMID 36362284, 2022). "Also, cortactin-related RhoA activity is documented to show cellular proliferation in head and neck squamous cell carcinoma." (PMID 33407452, 2021). "Furthermore, based on their immunohistochemistry analyses, RhoA was suggested to be a promising biomarker of malignancy and/or aggressiveness in head and neck squamous cell carcinoma (HNSCC)." (PMID 24191200, 2013). "In head and neck squamous cell carcinoma (HNSCC), CXCL14 expression and secretion and its anti-tumor effect is negatively regulated by RhoA/ROCK pathway." (PMID 26733763, 2016).
lupus (7 papers, 2016 to 2025). "The RhoA/ROCK pathway has been implicated in lupus pathology in a prior study that showed that increased phosphorylation of the ezrin, radixin, moesin (ERM) proteins interact with CD44 to promote the adhesion, migration and inflammatory response of T lymphocytes." (PMID 37790522, 2023). "Our previous work has shown that the expression of RhoA is significantly higher in lupus T cells and that targeting RhoA can reduce their production of IL-2." (PMID 38243295, 2024). "Previous studies have reported that inhibition of RhoA/ROCK signaling significantly reduced anti-dsDNA antibody levels in lupus-prone NZB/NZW F1 mice, effectively alleviating renal damage and reducing mortality." (PMID 38243295, 2024). "We investigated differences in the expression of RhoA mRNA in PBMCs between patients with SLE and healthy controls by quantitative, real-time PCR (RT-PCR) and observed a 3-fold higher level of RhoA mRNA in the lupus group." (PMID 38243295, 2024). "Accordingly, we examined the activation state of RhoA and its downstream actions in the PBMCs of lupus patients, and assessed the consequences of RhoA pathway inhibition on selected type I IFN-induced genes relevant to immune dysregulation." (PMID 37790522, 2023). "Previous studies have reported that inhibition of RhoA/ROCK signaling significantly reduced anti-dsDNA antibody levels in lupus-prone NZB/NZW F1 mice, effectively alleviated renal damage and reducing mortality." (PMID 37790522, 2023). "We investigated differences in the expression of RhoA mRNA in PBMCs between patients with SLE patients and healthy controls by quantitative, real-time PCR (RT-PCR) and observed a 3-fold higher level of RhoA mRNA in the lupus group." (PMID 37790522, 2023). "The RhoA/ROCK signaling pathway has been implicated in immunoinflammatory diseases, such as systemic lupus erythematosus, myasthenia gravis, inflammatory cardiovascular diseases, and inflammatory airways diseases." (PMID 31600977, 2019). "Our previous study has demonstrated a significant increase in RhoA expression in lupus T cells." (PMID 38243295, 2024). "There has been growing evidence to indicate that RhoA mediates phosphorylation of STAT-3 and STAT-5 in several cell types via ROCK and that targeted RhoA-ROCK inhibition modulates STAT-3 phosphorylation to shift toward a pathologic Th17/Treg imbalance in patients with lupus." (PMID 38243295, 2024). "In the present report, RhoA mRNA expression further is shown to be higher in the PBMCs of lupus patients when compared to healthy controls, and expression levels correlate positively with type I IFN scores and interferon-induced genes, including CXCL10, OAS1, IFIT3, and MX1." (PMID 38243295, 2024). "Conceivably, interruption of this feedback pathway by the pharmacologic targeting RhoA could provide a means to reset type I IFN activation in a manner that would be therapeutically beneficial in lupus but preserve necessary anti-infective responses." (PMID 38243295, 2024). "In our project,RhoA mRNA expression further has been shown to be higher in the PBMCs of lupus patients when compared to healthy controls, and expression levels correlate positively with type I IFN scores and interferon-induced genes, including CXCL10, OAS1, IFIT3 and MX1." (PMID 37790522, 2023). "There has been growing evidence to indicate that RhoA mediates phosphorylation of STAT-3 and STAT-5 in several cell types via ROCK, and that targeted RhoA-ROCK inhibition modulates STAT-3 phosphorylation to shift the pathologic Th17/Treg imbalance in patients with lupus." (PMID 37790522, 2023). "Conceivably, interruption of this feedback pathway by the pharmacologic targeting RhoA could provide a means to reset type I IFN activation in a manner that would therapeutically beneficial in lupus but preserve necessary physiologic responses to infection." (PMID 37790522, 2023).
lupus (continued). "GEF–H1 exemplifies functional pleiotropy in immune dysregulation: In systemic lupus erythematosus (SLE), PPP2R2A‐mediated dephosphorylation of GEF–H1 activates the RhoA–ROCK axis, driving pathogenic IL‐17/IFN‐γ production in T cells." (PMID 41020039, 2025). "We confirmed RhoA to be highly expressed in the PBMC population of SLE patients when compared to healthy controls, and especially in those lupus patients with high type I IFN scores." (PMID 37790522, 2023). "We can speculate that TCONS_00195779-miR-31-5p-RhoA may be involved in the pathogenesis of lupus." (PMID 30836987, 2019). "We confirmed RhoA to be highly expressed in the PBMC population of SLE patients when compared to healthy controls, especially in those lupus patients with high type I IFN scores." (PMID 38243295, 2024). "The RhoA/ROCK inhibitor in turn reduced type I IFN-induced STAT-1 phosphorylation and ISRE reporter gene expression, as well as OAS1 and CXCL10 in human lupus PBMCs." (PMID 37790522, 2023).
multiple myeloma (7 papers, 2015 to 2025). "WNT3 contributed to cell adhesion–mediated drug resistance (CAM-DR) of myeloma cells via the WNT/RhoA/ROCK pathway of myeloma cells in an autocrine manner." (PMID 38711026, 2024). "Research about bortezomib-induced thrombocytopenia during relapsed multiple myeloma therapy showed the accumulation of RhoA in megakaryocytes enhanced phosphorylation of myosin light chain and inhibited proplatelet formation." (PMID 35354403, 2022). "Myeloma-secreted CCL3 and paracrine CCR5 significantly promoted M2 macrophage polarization by activating PI3K/AKT/RhoA signaling, which in turn enhanced myeloma proliferation, inhibited apoptosis, and reduced Bortezomib sensitivity." (PMID 39953613, 2025). "While the role of SDF-1α in the metastatic spread in solid tumors has been clearly established, its role in activation of RhoGTPases has only been described in the context of multiple myeloma where SDF-1α binding to its receptor CXCR4 induces chemotaxis and motility through RhoA activation." (PMID 26231656, 2015).
type 2 diabetes (7 papers, 2014 to 2023). "RhoA has far reaching implications in many diseases including type-2 diabetes, its activity is upregulated by oxidative stress and hyperglycemia." (PMID 30972066, 2019). "The present study showed that RhoA/ROCK was involved in atrial fibrosis, and fasudil hydrochloride hydrate ameliorated atrial fibrosis through the RhoA/ROCK pathway in rats with type 2 diabetes." (PMID 25120610, 2014). "Two targets, PRKCA and RHOA proteins, and four signaling pathways, including the mTOR signaling pathway, Type II diabetes mellitus, and Ras and Rap1 signaling pathway, were predicted and considered as key nodes and pathways through which Forsythiaside ameliorated DKD podocytopathy." (PMID 36712665, 2022). "The aim of this study was to assess levels of ROCK activation and some of the RhoA/ROCK cascade molecules in peripheral blood mononuclear cells (PBMCs) in type 2 diabetic patients under current treatment and its relationship with LV function and levels of Angiotensin II." (PMID 32375786, 2020). "Therefore, the present study focused on the expression and function of the RhoA/ROCK pathway in a rat model of type 2 diabetes." (PMID 25120610, 2014). "Additionally, the RhoA/ROCK pathway is involved in atrial fibrosis in rats with type 2 diabetes." (PMID 25120610, 2014). "The results suggested that RhoA/ROCK was involved in atrial fibrosis, and that fasudil hydrochloride hydrate ameliorates atrial fibrosis through the RhoA/ROCK pathway in rats with type 2 diabetes." (PMID 25120610, 2014).
allergic disease (6 papers, 2018 to 2025). An immune response that occurs following re-exposure to an innocuous antigen, and that requires the presence of existing antibodies against that antigen. "Several studies have documented the close association of RhoA with allergic diseases, whereas one study has indicated the regulatory effect of DEK on RhoA." (PMID 39668431, 2025). "This suggests not only a critical role for RhoA in regulating EC permeability in diseases like allergy and anaphylaxis, but also the rescue discrepancy between RhoA KO and ROCK inhibition implies possible roles for other Rho GTPases in this response." (PMID 31174284, 2019). "SHLI-induced pseudo-allergic reactions were mediated by the activation of the RhoA/ROCK signaling pathway." (PMID 29487527, 2018). "Ablation of RhoA shows effects on suppressing allergic diseases in animal model studies." (PMID 35910793, 2022). "Previous studies also noted the involvement of RhoA in the pathogenesis of allergic diseases." (PMID 35910793, 2022). "Blocking RhoA/ROCK signaling pathway can reduce vascular permeability and inhibit the occurrence of a pseudo-allergic reaction." (PMID 36782216, 2023).
B-cell lymphomas (6 papers, 2016 to 2025). "In B-cell lymphomas, RHOA mutations are rarely observed, but mutations affecting the upstream molecules, such as GNA13, that negatively affect RHOA functions, are moderately frequent." (PMID 35954378, 2022).
ciliopathies (6 papers, 2013 to 2023). "RhoA has been shown to contribute to the molecular pathology of ciliopathies: increased RhoA levels were observed in dermal fibroblasts from ciliopathy patients with TMEM216 mutations." (PMID 33392209, 2020). "RhoA activation and a perturbed cytoskeleton have been observed in a variety of ciliopathies, including NPHP, suggesting that RhoA may be implicated in the pathogenesis of NPHP." (PMID 36834937, 2023). "However, the mechanism underlying RhoA activation in ciliopathies remains unclear." (PMID 36834937, 2023). "However, the mechanisms underlying RhoA activation in ciliopathies remain largely unknown." (PMID 36834937, 2023). "Aberrant activation of RhoA, disorganized actin filaments, and disturbed ciliogenesis have long been observed in various ciliopathies." (PMID 36834937, 2023). "Recent evidence on the role of the RhoA/ROCK pathway in ciliogenesis heightened interest in the studies of actin regulation in relation to ciliopathies." (PMID 38292052, 2023). "Various studies have shown that ciliopathies, such as Lowe, Joubert, and Bardet-Beidl syndromes, have defects in RhoA or Rac1 localization or activity." (PMID 26044959, 2015). "Aberrantly increased RhoA activity has been observed in many ciliopathies." (PMID 36834937, 2023). "The data presented here are consistent with our prior hypothesis that increased actin polymerization, through RhoA dysregulation, disrupts the normal function of primary cilia and underlies the pathogenesis of BBS and possibly other ciliopathies." (PMID 23716571, 2013). "Dysregulation of the RhoA/ROCK pathway leads to a highly disorganized cytoskeleton in cyst cells in ADPKD, as well as in other ciliopathies." (PMID 36834937, 2023). "Given the persistent deregulation of RhoA signaling and actin polymerization in many models of renal ciliopathies, including ADPKD, NPHP and BBS, it would be reasonable to test Fasudil in human trials to treat ciliopathies, e.g., ADPKD or NPHP." (PMID 38292052, 2023). "Our findings suggest that RHOA activation downstream of SMO might be unaffected in cells with abnormal cilia, as a consequence of ciliopathies or oncogenic transformation, since many cancer cells lack primary cilia." (PMID 30148884, 2018).
colon adenocarcinoma (6 papers, 2011 to 2025). "BRAFV600E provides human colon adenocarcinoma cells with a more "aggressive" phenotype and consequential migrating and invading properties, mainly through RhoA activation, regulated by MEK pathway." (PMID 21943101, 2011). "Finally, we explored whether the increased activity of the stromal RhoA/ROCK/myosin pathway could affect colon adenocarcinoma cell growth." (PMID 40842027, 2025). "Mechanistically, high PDPN expression in stromal cells upregulates CAF activation markers, enhances RhoA-mediated cytoskeletal contractility, and promotes ECM protein synthesis, thereby fostering a niche that supports colon adenocarcinoma cell growth." (PMID 40842027, 2025). "Linkage between the RhoA-ROCK and the BRAF-ERK-MAPK pathway has previously been described, for example in the control of osteogenic gene expression and in colon adenocarcinoma cells, where it induced cell migration and invasion." (PMID 26828592, 2016). "CCNA2 expression was lower in metastases relative to that in matched primary colon adenocarcinoma, suggesting that CCNA2 negatively controlled motility by promoting RhoA activation, thereby showing a new function of CCNA2 in cytoskeletal rearrangement and cell migration." (PMID 40345591, 2025). "Depletion of RhoA substantially impaired both acquired properties with more profound effect in Caco-BR13 cells, further illustrating its central role in the BRAFV600E oncogene-induced transformation of colon adenocarcinoma cells." (PMID 21943101, 2011).
cyst (6 papers, 2013 to 2025). A sac-like closed membranous structure that may be empty or contain fluid or amorphous material. "Our results indicate that dysregulation of the RhoA/ROCK axis in ADPKD is likely to be a major factor in cyst initiation and should stimulate the development of further therapeutic approaches in this area." (PMID 32663194, 2020). "PC1 loss-of-function was shown to induce RhoA activation, which, in turn, triggered the Rho kinase- and myosin phosphorylation-dependent activation of the Hippo pathway effector YAP and its paralog TAZ, facilitating cyst formation." (PMID 38891116, 2024). "ROCK inhibitors have successfully improved cyst formation in ADPKD, suggesting that the cytoskeletal-associated RhoA/ROCK pathway may be a major factor in cyst initiation." (PMID 36834937, 2023). "The effects of Pkhd1 on SMURF and RhoA activity may also contribute to cyst formation by other mechanisms." (PMID 28798345, 2017). "Together, these findings demonstrate RhoA rescues responsiveness of CDH3-/- cysts to HGF, enabling cyst protrusion formation, correlating to cyst morphology and matrix deformation rates similar to WT cysts." (PMID 41424915, 2025). "Blocking of RhoA/ROCK signaling by the ROCK inhibitor Y-27632 restores cilia length and the disorganized actin filaments in PKD1KD cells and reduces cyst formation in PKD1KO mice." (PMID 36834937, 2023). "In the present study, the knockdown of GEF-H1 abrogated RhoA and MLC2 activation in NPHP1KO mice, with alleviated renal pathological changes, including cyst formation, interstitial fibrosis, and inflammation, as indicated by macrophage infiltration." (PMID 36834937, 2023). "We found that the GEF-H1/RhoA pathway was activated in the kidney of NPHP1 knockout (NPHP1KO) mice and NPHP1 knockdown (NPHP1KD)HK2cells and that it was involved in cyst formation, fibrosis, and inflammation." (PMID 36834937, 2023). "Targeting the RhoA/ROCK pathway inhibited cyst formation in vitro and in vivo, indicating its relevance to ADPKD pathogenesis and for developing new therapies to inhibit cyst initiation." (PMID 32663194, 2020). "While PC-loss-induced ITGB1 activation may not be a prerequisite for initial RhoA activation/MRTF induction, sustained ITGB1 activation/expression (promoted by increased cell contractility, stretching of the cyst wall, or ECM stiffening) may signify a potent feed-forward mechanism." (PMID 38891116, 2024).
dilated cardiomyopathy (6 papers, 2015 to 2025). Cardiomyopathy which is characterized by dilation and contractile dysfunction of the left and right ventricles. "Then again, cardiomyocyte-specific knockout of RhoA resulted in an accelerated and more severe dilated cardiomyopathy after chronic pressure overload." (PMID 40911671, 2025). "Fatty acid β-oxidation, ILK, RHOA, and dilated cardiomyopathy signaling characterize LDM exposure whereas two other pathways (necroptosis and GP6 signaling) characterize SDM exposure." (PMID 36835504, 2023). "Finally, we found that patients with idiopathic dilated cardiomyopathy without causal mutations for dilated cardiomyopathy showed reduced cardiac expression of RhoA and Parkin." (PMID 36758801, 2023).
head and neck cancer (6 papers, 2009 to 2022). A primary or metastatic malignant neoplasm affecting the head and neck. "Moreover, reconstitution of constitutive active RhoA or RhoC in these PKCε-deficient head and neck cancer cells rescued the loss-of-function motility defect providing direct evidence that RhoA and RhoC is downstream of the PKCε signaling cascade." (PMID 19228372, 2009). "HA treatment activates and promotes EGFR-mediated pathways including Ras, RhoA, Rho kinase, and phosphatidylinositol-3 (PI-3) kinase signaling in head and neck cancer." (PMID 23855374, 2013). "PKCε regulates motility and invasion in models of breast as well as head and neck cancer, at least partially through RhoA and RhoC GTPases." (PMID 22384062, 2012).